CTLA4 (cytotoxic T-lymphocyte associated protein 4)
Diseases named in the same sentence as CTLA4 in open-access papers (continued):
Sharing a sentence is not in itself a finding about the gene and the disease.
cancer (continued). "The best-characterized immunological checkpoints with a major impact on both cancer growth and cancer therapy are cytotoxic T-lymphocyte antigen 4 (CTLA-4) and programmed death receptor 1 (PD-1) and their respective ligands." (PMID 26313362, 2015). "Consistent with a pivotal role for CD80 in cancer immune surveillance, neutralization of CD80 caused a significant increase in HGD, whereas enhancing CD80 signaling with anti-CTLA4 protected mice from colon carcinogenesis progression." (PMID 25595911, 2015). "Targeting CTLA-4 is a recent strategic approach in cancer control: blocking CTLA-4 enhances an antitumor immunity by promoting T-cell activation and cytotoxic T-lymphocyte proliferation." (PMID 26337719, 2015). "In summary, current study results show the importance of investigating the optimal dose, schedule, and combination of anti-CTLA-4 antibodies with other therapy options to ensure high patient safety and efficacy in selected cancer entities." (PMID 26500646, 2015). "Subsequently FDA approval of antibodies targeting CTLA-4 and PD-1 has had profound implications on the outlook of immune-mediated therapies to treat cancer." (PMID 26580645, 2015). "Treatment with monoclonal antibody specific for cytotoxic T lymphocyte associated antigen-4 (CTLA-4), a checkpoint protein expressed on T-lymphocytes has emerged as an effective cancer therapy." (PMID 26079374, 2015). "It is for this reason that CTLA-4 has attracted attention as a target molecule of cancer immunotherapy." (PMID 25365349, 2014). "Checkpoint blocking antibodies targeting regulatory molecules on T cells such as CTLA-4 and PD-1 have reinvigorated the field of cancer immunotherapy." (PMID 25642417, 2014). "The success of anti-CTLA-4, anti-PD-L1 and anti-PD-1 antibodies in the treatment of various cancer types undoubtedly supports the idea of targeting inhibitory mechanisms that drive CTL dysfunctionality." (PMID 25338019, 2014). "Interventions such as concurrent CTLA-4 blockade and vaccination, combined CTLA-4 and PD-1/PD-L1 blockade, and Treg depletion have been successfully used to ameliorate Treg-mediated immune pathologies and cancer." (PMID 24639678, 2014). "For some cancer immunotherapies, such as blockade of the inhibitory T cell signaling molecule CTLA4, autoimmune toxicity shows a positive correlation with therapeutic response." (PMID 24672527, 2014). "Pre-clinical and clinical trials of anti-CTLA-4 mAbs have been conducted for the treatment of other cancers, including colon, breast, lung, ovarian, and prostate cancers." (PMID 25365349, 2014). "These profiles warrant further assessment and validation of their utility for patient selection in other, preferably randomized, clinical trials of GM-CSF-based therapy and/or CTLA-4 blockade or other forms of cancer immunotherapy." (PMID 26196012, 2014). "A recent phase III clinical trial reported that therapy with CTLA-4–blocking antibodies imparted a significant survival benefit in approximately 30% of patients with other cancer, making this drug a promising treatment for glioblastoma." (PMID 25346943, 2014). "Cytotoxic T-lymphocyte antigen 4 (CTLA-4), an immune-checkpoint receptor and regulator of T-cell activation, has become an important therapeutic target for immunotherapy in cancer." (PMID 25349698, 2014). "Animal models and clinical trials support a role for CTLA-4 blockade in breaking the tolerance to both human cancer antigens and self-antigens." (PMID 24594636, 2014). "Fully human anti-CTLA-4 monoclonal antibodies (mAbs), ipilimumab and tremelimumab, were developed for the treatment of cancer patients." (PMID 25365349, 2014). "Eighth, a promising strategy to treat cancer consists in potentiating the naturally occurring immune response of the patient, through blockade of the immune checkpoint molecules CTLA-4, PD-1, or PD-L1." (PMID 24860567, 2014).
cancer (continued). "The combination of radiotherapy and CTLA-4 blockade is a promising potential cancer therapy, although further study is required." (PMID 24686897, 2014). "Although CTLA-4-targeted therapy is an attractive method for the treatment of various cancers, the therapy is beset by several problems." (PMID 25365349, 2014). "An exciting development over the past few years has been the use of anti-CTLA-4 in so-called checkpoint blockade in the treatment of cancers." (PMID 25538704, 2014). "Blocking CTLA-4 function and enhancing T cell activation, several different types of malignant neoplasms in tumor-transplanted mice were inhibited or cured, and owned long-lasting antitumor immunity." (PMID 24710335, 2014). "Several approaches are now being investigated to boost anti-cancer immune response, either by inhibiting immune checkpoints (as CTLA-4, PD-1, and PD-L1) or by developing vaccines of cancer antigens." (PMID 25505733, 2014). "Clinical trials are on-going evaluating the use of anti CTLA-4 antibodies in other cancer indications including lung, colorectal, renal, and ovarian." (PMID 24605114, 2014). "The inhibitory receptor, Cytotoxic T-lymphocyte-associated antigen 4 (CTLA-4), was the first checkpoint receptor to be extensively and successfully pursued as an anti-cancer target." (PMID 24605114, 2014). "It is of some interest that the latest immunotherapies employing antibodies to CTLA-4 and the PD-1 ligand now permit the T-cells to function and kill the cancer cells." (PMID 25238040, 2014). "The expression of CTLA-4 is upregulated following T-cell activation and the pathway has been shown to play an important immunomodulatory role in cancer." (PMID 23626745, 2013). "Among the incoming cancer immunotherapy strategies, antibody blockade of the inhibitory molecules CTLA4 and PDL1 appears a promising approach." (PMID 23359812, 2013). "The selective enhancement of T cell activation, using the CTLA-4-Ig protein or PD-1 blocking antibodies, has been demonstrated to be a suitable strategy for cancer immunotherapy." (PMID 23497351, 2013). "Ipilimumab was designed and developed to block the cytotoxic T-lymphocyte-associated antigen 4 (CTLA-4), thereby increasing the T-cell activity and promoting antitumor activity in patients with cancers." (PMID 23533766, 2013). "The potential for these agents in the treatment of patients with advanced cancers, including their incorporation into combination regimens (e.g., PD-1- plus CTLA-4-blocking antibodies), is significant, and further data are eagerly awaited." (PMID 24403232, 2013). "In this meta-analysis, we investigated the association between CTLA-4 60G/A (rs3087243) and CTLA-4 -1661A/G (rs4553808) and cancer risk." (PMID 24376736, 2013). "In conclusion, our results demonstrate that anti-CTLA-4 therapy and cytotoxic chemotherapy can have a clear synergistic effect in the treatment of cancer." (PMID 23626745, 2013). "Ipilimumab has supported the development of the immuno-oncology discipline, and CTLA-4 will hopefully be the first of many targets to be successfully exploited to fight cancer in the future." (PMID 23772560, 2013). "Genes that have been previously associated with MD and various other cancers showed differential marks that are either MD-induced (MX1, CTLA-4, EAF2 and GAL) or line-specific (IGF2BP1 and MMP2)." (PMID 23072359, 2012). "PD-1 and CTLA-4 have been extensively studied, and blocking antibodies have already shown clinical benefit for cancer patients." (PMID 22347406, 2012). "Cytotoxic T-lymphocyte-associated antigen 4 (CTLA-4), which competes with CD28 for B7 binding, has been widely accepted as a new promising target for cancer immunotherapy." (PMID 23133541, 2012). "The differences in outcomes between the tolerized and non-tolerized models also provide a potential explanation for the low efficacy of CTLA4 blockage approaches in cancer immunotherapy trials." (PMID 21779410, 2011).
cancer (continued). "Toxicities seen on this trial were largely consistent with the known toxicities of anti–CTLA-4 therapies in a population with advanced cancer." (PMID 20143434, 2010). "Tremelimumab (CP-675, 206) is another fully human monoclonal antibody specific for human cytotoxic T lymphocyte-associated antigen 4 (CTLA-4, CD 152) in clinical development for patients with cancer." (PMID 24281101, 2010). "The brilliant results of a phase 1 clinical trial using a fully humanized antagonistic CTLA4 monoclonal antibody highlight the potential immunotherapeutic value of antibody-based therapies for cancer." (PMID 19473517, 2009). "Previous reports have documented that CTLA-4 blockade is a feasible strategy for potent in vivo expansion of antigen specific T cells, in particular in the context of cancer vaccination." (PMID 17662155, 2007). "Indeed, we analyzed transcriptomic data from tumors collected prior to ICB treatment across six independent datasets encompassing multiple cancer types treated with anti–PD-1/–PD-L1 or anti–CTLA-4 therapies." (PMID 41486951, 2026). "This review provides a comprehensive overview of the regulation and therapeutic targeting of immune checkpoint proteins in cancer, covering both classical checkpoints, including PD-1, PD-L1, and CTLA-4, and emerging targets such as LAG-3, TIM-3, TIGIT, BTLA, SIRP-α, CD200, ILT4, and CD24." (PMID 42279386, 2026). "The broad expression and function of CTLA-4 across multiple immune cell types highlight its central importance in maintaining immune homeostasis, as well as its potential as a therapeutic target in cancer immunotherapy." (PMID 41486149, 2026). "Immune checkpoint inhibitors such as anti-PD-1, anti-PD-L1, and anti-CTLA-4 antibodies that have transformed cancer therapy and expanded the therapeutic options in humans could offer the same clinical benefit in canine cancer patients." (PMID 42274559, 2026). "Our results provide a rationale for intratumoural anti-CTLA4 strategies in oligometastatic and early-stage cancers and indicate that high intratumoural activated Treg cell and FcγR+ M2 macrophage numbers are prerequisites for efficacy of combined anti-CTLA4 and anti-PD1." (PMID 42056527, 2026). "Furthermore, an early increase in clonal proliferation of PD-1+ CD21-low B cells was observed and correlated with ir-AE in cancer patients following anti-PD-1 and anti-CTLA-4 therapies." (PMID 40109334, 2025). "Low ICOS (<25th percentile RNA rank; found in 44% of 514 cancers) was independently associated with not-high (<75th percentile RNA rank) PD-1, not-high PD-L1, not-high CTLA-4, and low ICOS ligand." (PMID 40297627, 2025). "Radiation therapy promotes immunogenic cell death, which leads to antigen release and immune cell activation, whereas immunotherapy enhances the immune system’s ability to recognize and destroy cancer cells by targeting checkpoint pathways like PD-1/PD-L1 and CTLA-4." (PMID 40387780, 2025). "Immune checkpoints, including cytotoxic T-lymphocyte-associated antigen 4 (CTLA)-4, the programmed cell death protein 1 (PD-1) receptor, and its ligands (PD-L1 and PD-L2), suppress T-lymphocyte activity, which can detect cancer antigens as foreign and destroy them." (PMID 41375037, 2025). "The observed increase in mutation load in the low-risk group, alongside the elevated expression of immune checkpoint markers such as CD24, CD28, CTLA-4, and TIGIT in the high-risk group, underscores the complex interplay between genetic mutations and immune escape mechanisms in cancer development." (PMID 40510341, 2025). "This further adds to the growing body of literature that shows that a lower NLR could be a peripheral biomarker for the prediction of irAEs and cancer outcomes amongst those treated with either class of ICI (PD-1/PD-L1 or CTLA-4)." (PMID 40563660, 2025). "Nevertheless, some research studies have shown an absence of association between CTLA-4 polymorphisms and certain cancer types in particular populations." (PMID 41141615, 2025).
cancer (continued). "A particular importance focuses on overexpression of immunosuppressive checkpoints, such as cytotoxic T-lymphocyte-associated protein 4 (CTLA-4), Programmed Death 1 (PD-1), and Programmed Death-Ligand 1 (PD-L1) within the TME, which can impair the immune system’s ability to destroy cancer cells." (PMID 41226048, 2025). "The Ras association domain family 1 isoform A (RASSF1A), CTLA-4, and signal transducer and activator of transcription 4 (STAT4) genes are involved in the regulation of the cell cycle, apoptosis, and the autoimmune response against cancer." (PMID 41303553, 2025). "Additionally, the blockade of immune checkpoints, such as PD-1/PD-L1 and CTLA-4, has emerged as a popular approach for treating malignant tumors." (PMID 40809844, 2025). "Our analysis of HCC using the TCGA database confirmed the correlation of TKT with additional ICP genes, including CD44, CD80, CD86, and CTLA-4, which may explain the association of TKT overexpression with poorer prognoses in patients with cancer." (PMID 40230848, 2025). "In addition, AURKA expression was significantly and positively correlated with immune checkpoint targets such as CD274, LAG3, and CTLA4 in most cancer types." (PMID 40718709, 2025). "The approval of antibodies against cytotoxic T-lymphocyte-associated protein 4 (CTLA-4) and programmed cell death protein 1 (PD-1)/PD-L1 has significantly transformed the cancer treatment landscape, leading to a number of clinical trials assessing ICI efficacy." (PMID 41244934, 2025). "Additionally, ipilimumab, an anti-CTLA-4 therapy, has been approved, particularly in combination with other ICIs for cancers such as cutaneous melanomas." (PMID 39857692, 2025). "Tumors achieve immune escape partly through adaptive checkpoints such as Programmed cell death protein 1 (PD-1)/Programmed death-ligand 1 (PD-L1) and Cytotoxic T-lymphocyte-associated protein 4 (CTLA-4), which normally restrain T-cell activity but are co-opted by cancers to induce T-cell exhaustion." (PMID 41514569, 2025). "In cancer, increased CTLA-4 expression in the TME is crucial for immune evasion." (PMID 41233805, 2025). "Moreover, the synergistic effect of B68 with anti‐CTLA4 therapy further enhances antitumor immunity, and its ability to induce senescence in cancer cells triggers a strong protective response by dendritic and CD8+ T cells." (PMID 39721027, 2025). "CTLA-4 blockade relies on Bacteroidales species to promote successful anti-cancer T-cell responses." (PMID 40075661, 2025). "Several FMD trials have been initiated, including an FMD-ICI trial examining a 4-day FMD in advanced cancer patients on anti-PD-1/PD-L1 or anti-CTLA4 ICIs, alone or in combination (NCT06438588), and NCT06671613 for plant-based FMD in patients with metastatic NSCLC undergoing pembrolizumab treatment." (PMID 41425618, 2025). "Notably, checkpoint inhibitors targeting the PD-1/PD-L1 or CTLA-4 have been approved for the treatment of various cancers." (PMID 40838069, 2025). "CTLA‐4 is the first target immune checkpoint molecule used in cancer treatment." (PMID 40243372, 2025). "CTLA-4, predominantly expressed in regulatory T cells, exhibits elevated levels in activated conventional T cells and serves to downregulate immune responses in cancer contexts." (PMID 41350575, 2025). "However, cancer cells exploit immune checkpoint proteins such as CTLA4 and PD1 to evade immune attack." (PMID 40352591, 2025). "Due to immune evasion mechanisms by cancer as well as chronic inflammation in the cancer microenvironment, laryngeal SCC is frequently associated with upregulation of immune checkpoints such as PD-1, PD-L1, and CTLA-4." (PMID 40427066, 2025). "Moreover, the levels of other checkpoint molecules, such as TIM3, TIGIT, and CTLA4, were significantly associated with CXCL5 in multiple forms of cancer." (PMID 39670859, 2025).
cancer (continued). "The combination of anti‐PD‐1 and anti‐CTLA‐4 therapies has shown favorable efficacy in various cancers, such as melanoma, cervical cancer, and lung cancer, where it can significantly prolong patient PFS and OS compared with PD‐1 inhibitors alone, while also exhibiting manageable safety profiles." (PMID 40686307, 2025). "Many studies suggest that combining novel immune checkpoint inhibitors with traditional ICIs (such as PD-1/PD-L1 and CTLA-4 inhibitors) could significantly improve cancer treatment outcomes and patient survival." (PMID 40012016, 2025). "Strikingly, ACACA expression exhibited significant negative correlations with the immune checkpoint-related genes (PDCD1, LAG3, LAGLS9, IDO1, CD244, CTLA4 and TIGIT), while showing positive associations with other genes (TGFBR1, KDR, IL10RB, CD160 and CD274) across most cancer types." (PMID 41169354, 2025). "In cancer immunotherapy, aptamers targeting immunological checkpoint molecules, including CTLA-4, TIM-3, and LAG-3, might replace monoclonal antibodies." (PMID 40870970, 2025). "In contrast, CD4+ T cell RNA-seq analysis revealed the specific expansion of cluster 2 in all 4 patients with cancer following anti–CTLA-4 and anti–PD-1 combination therapy, which corresponded to the time at which autoreactive B cells accumulated in the periphery." (PMID 41026527, 2025). "These drugs, such as monoclonal antibodies that block CTLA-4 (cytotoxic T-lymphocyte-associated protein 4), LAG-3 (lymphocyte activation gene 3), and PD-1 or its ligand (PD-L1), restore T-cell immune responses in different cancer types." (PMID 39857724, 2025). "Co-inhibitory receptors on T cell surfaces called cytotoxic T lymphocyte antigen 4 (CTLA-4) and programmed cell death 1 (PD-1) help to reduce T cell-mediated immune responses; however, cancer cells use these inhibitory molecules to encourage tumor tolerance and T cell exhaustion." (PMID 40149618, 2025). "However, the FDA-approved inhibitors for cancer treatment target only a few checkpoints, such as CTLA-4, PD-L1 and PD-1." (PMID 41024300, 2025). "Notably, immune checkpoints, including PD-1/PD-L1 and CTLA-4, have emerged as critical regulators of immune responses in cancer, presenting promising targets for immunotherapeutic interventions." (PMID 39857769, 2025). "Elevated expression levels of immune checkpoints, such as PD-1, programmed cell death ligand 1 (PD-L1), and cytotoxic T-lymphocyte-associated protein 4 (CTLA-4), have been associated with enhanced clinical responses to ICB therapy in cancer patients, as demonstrated in prior studies." (PMID 41431699, 2025). "Immune checkpoint inhibitors (ICIs) are generated antibodies that bind selectively and block the checkpoint proteins PD-1, PD-L1, and CTLA-4 expressed by tumor cells to escape the T cell-mediated antitumor response, therefore allowing T cells to recognize and eliminate cancer cells." (PMID 40940933, 2025). "Other than being expressed in immune cells, CTLA-4 and PD-1 are also expressed in cancer cells." (PMID 40109334, 2025). "The FPMF@CpG ODN NCs exhibited higher synergistic photo-chemo-immunotherapy for cancer due to the highly effective photothermal conversion of MoS2 nanosheets, overproduction of ROS induced by FePt, and the increase immune cells activated by CpG ODNs and CTLA4." (PMID 40017598, 2025). "Recent advancements in immunotherapy, particularly immune-checkpoint blockade (ICB) targeting anti-PD1/PD-L1 and anti-CTLA4, have facilitated a paradigm shift in cancer treatment, demonstrating substantial survival benefits across various cancer types, including HCC." (PMID 40051497, 2025). "CTLA-4 is a well-established target in immune checkpoint and cancer immunotherapy." (PMID 40821770, 2025). "Two significant checkpoints involved in cancer outcomes are PD-1/PD-L1 and CTLA-4 pathways." (PMID 41228294, 2025).